CXCR4 (C-X-C motif chemokine receptor 4)
Diseases named in the same sentence as CXCR4 in open-access papers (continued):
Sharing a sentence is not in itself a finding about the gene and the disease.
tumor (continued). "As a consequence of CXCR4 engagement, in two different tumor models, mice develop an antitumor immune response that depends on CD8+ T cells and acquire antitumor immune memory." (PMID 33956406, 2021). "The importance of CXCL12/CXCR4 in intraosseous tumor cell dissemination is further underpinned by the observation that inhibition of CXCR4 remobilizes PrCa DTCs back into circulation, thus possibly increasing their vulnerability to anticancer treatment." (PMID 34064859, 2021). "In vitro CM from tumor-exposed human monocytes promoted TNF-α-induced CXCR4 expression on HUVECs via the Raf-Erk pathway." (PMID 34209679, 2021). "Silencing of CXCL12 altered the homeostatic autocrine and paracrine CXCR4 signaling to endocrine communication in the tumor microenvironment, leading to tumor progression and metastases." (PMID 34321012, 2021). "Previous studies have also shown that MSCs expanded under hypoxic conditions (referred to as hypoxic MSCs) exhibit greater proliferation, reduced senescence, increased stemness, and increased homing to tumor sites via upregulation of CXCR4." (PMID 34068264, 2021). "In many types of cancer cells, chronic hypoxia does not increase the expression of CXCL12, although with an increased expression of CXCR4, the sensitivity of tumor cells to CXCL12 increases." (PMID 33467722, 2021). "In the process of homing, tumor cells overexpressing CXCR4 or CXCR7 have higher potential to survive the circulation stage, guarded by CXCL12 secreted by bone stromal cells." (PMID 34830862, 2021). "In a preclinical study using an ovarian cancer model, dual blockade of the CXCL12/CXCR4 and PD-1-PD-L1 signaling cascades effectively reduces tumor burden and prolongs survival in tumor-bearing mice." (PMID 34771482, 2021). "SDF-1 expression by tumor-infiltrating immune cells (TIC) showed a strong correlation with CXCR4 positive TIC and a moderate correlation with CD8 T-cell density as well as pCXCR4 positive TIC on a protein level." (PMID 33436863, 2021). "To evaluate the possible presence of BCSCs in surrounding tissue to the primary tumor, we assessed the expression of CXCR4 on BCSCs at different tissue intervals from the primary tumor site." (PMID 34778599, 2021). "The interface between tumour cells and neutrophils raised the manifestation of CXCR-4,7; MMP12,13; TGF-β, IL-6, the metastasis-related genes." (PMID 34336101, 2021). "The CXCR4/CXCL12 pathway is responsible for tumor metastasis, progression, induction of angiogenesis, and resistance to apoptosis." (PMID 34203877, 2021). "One of the drivers of tumor growth in this disease are genetic alterations of the gene CXCR4, which can be found in up to 40% of patients with this disease." (PMID 33669329, 2021). "CXCL12, and its receptor C-X-C receptor 4 (CXCR4), are related to hematopoiesis, angiogenesis, stem cell homing, and tumor progression and behavior." (PMID 34063285, 2021). "Consistent with a tumor promoting role of CXCL12–CXCR4 axis, CXCR4 neutralizing antibodies or CXCR4 knock down with shRNA reduces tumor cell invasion." (PMID 34298991, 2021). "In healthy tumor-free mice, cell surface expression of CXCR4 was significantly higher in chronologically aged (BrdUneg) than in non-aged (BrdUpos) blood neutrophils, whereas cell surface expression of L-selectin/CD62L and CXCR2 was significantly decreased." (PMID 34876407, 2021). "This indicated the enhanced tumour-initiation abilities of ALDH+CD44+CXCR4+CD24+- PCa cells in vitro, under androgen-deprived conditions in vitro." (PMID 34247196, 2021). "Reportedly, upregulation of CXCR4 in conjunction with the specific extracellular matrix (ECM) components were conducted to enhance tumor cell viability, and migratory and invasive abilities in various cancers." (PMID 34070538, 2021). "CXCR4 activation is also related to chemoresistance, maintenance of stem cell characteristics in tumor cells, and immunoresistance by recruiting regulatory T cells (Tregs) to the tumor microenvironment." (PMID 34079807, 2021).
tumor (continued). "The CXCL12/CXCR4 axis greatly contributes to certain tumor-mediated metastases and is thought to be a potential target of CXCR4 antagonists." (PMID 34722241, 2021). "Little is known regarding how CXCR4 expression by the tumor cells affects the vasculature, and it would be interesting if CXCR4 is sufficiently expressed in the tumor vasculature to be detected with the easily-accessible US." (PMID 34793563, 2021). "Next, we blocked SDF-1α/CXCR4 signalling by using AMD3100, a CXCR4 receptor antagonist, and investigated the effects of CXCR4 blockade on tumour growth." (PMID 33452462, 2021). "CD133+ esophageal CSCs contain a subgroup of cells characterized by the co-expression of CXCR4 and can evade the primary tumor and establish distant metastasis." (PMID 33710803, 2021). "As expected, we isolated ALDH+CD44+CXCR4+CD24+ cells from the tumour derived from the PDX model by cell sorting." (PMID 34247196, 2021). "The CXCR4/MIF and CXCR4/CXCL12 axis had been reported as the key elements of MSC migration toward tumor cells." (PMID 33933086, 2021). "Since the SDF-1/CXCR4 axis was considered as a significant signal axis in mediating the communication between tumor cells and stromal cells, the expression of CXCR4 was also detected in tumor tissue by using the IHC method." (PMID 34733839, 2021). "The T22 peptide facilitated the binding and internalization of the NPs in CXCR4+ tumor cells for targeted intracellular drug delivery." (PMID 34361141, 2021). "CXCR4 affects OC progression through enhancing tumor angiogenesis and suppressing immunity/inhibiting immunity." (PMID 32983229, 2020). "Even in MTC, it was found that the expression of CXCR4 correlates with advanced tumor stage and metastatic phenotype while that of CXCR7 declined in metastases." (PMID 32244473, 2020). "The imaging studies of the s.c. tumor models confirmed the advantage of 76Br-HZ270-1 for imaging CXCR4 expression, although high uptake was noted in the kidneys, intestine, and liver." (PMID 32239371, 2020). "In this study, we used TC-1 tumor-bearing mice to investigate the effect of treatment on CXCR4 expression." (PMID 31802362, 2020). "TGF-β2 and TGF-β1 can induce CXCR4 expression in several types of tumor cells and leukocytes, via TGF-β type I receptor-dependent non-Smad signaling pathways." (PMID 32245422, 2020). "CXCR4 as a CSC marker involved in tumor progression or poor survival of OS has been suggested by some studies." (PMID 31983166, 2020). "This subset was monitored because it has been shown that CXCR4 signaling is involved with tumour metastasis." (PMID 32882969, 2020). "One of the common mediators of cancer immunoresistance is the CXCL12/CXCR4 pathway due to enhanced recruitment of immunosuppressive cells in the tumor microenvironment." (PMID 33281749, 2020). "CXCR4, an important player in supportive interactions between tumor cells and other cells, participates in tumor cell proliferation, metastasis, angiogenesis, and the tumor microenvironment cross-talk in GBM." (PMID 32194542, 2020). "In summary, this study analyzed and provided the first evidence that CXCR4 was expressed in the majority of lung ASC tumor tissues." (PMID 31949484, 2020). "Blocking the CXCL12/CXCR4 interaction reduced tumor burden in preclinical models when used in combination with anti-PDL1." (PMID 33198059, 2020). "In this study, we also included a group of mice that received single-fraction tumor irradiation, followed by daily administration of the CXCR4-selective antagonist AMD3100." (PMID 31802362, 2020). "We chose CXCR4+ tumor models since they show high receptor overexpression allowing highly selective nanoparticle targeting." (PMID 33105866, 2020). "The cell lines were first treated with chemotherapeutic agents (cisplatin), SDF-1α, and AMD3100 (a CXCR4 antagonist), to determine the dependence of tumor proliferation on SDF-1α." (PMID 32344892, 2020).
tumor (continued). "The CXCL12/CXCR4 axis promotes tumor cell growth and propagation of distant metastases through the activation of epithelial-to-mesenchymal transition (EMT)." (PMID 32432042, 2020). "In a mouse model of inflammation-driven colorectal cancer, CXCR4 overexpression promotes trafficking of macrophages and myeloid-derived suppressor cells into the colon boosting tumor progression." (PMID 33096815, 2020). "Wnt signaling plays a pivotal role in CXCL12-induced tumor cell proliferation, as silencing CXCL12/CXCR4 signaling influences pancreatic cancer cell phenotypes and inhibits tumor cell proliferation in vitro via inactivation of the canonical Wnt pathway." (PMID 33363463, 2020). "The use of anti-CXCR4 drugs can also potentiate the anti-tumor activity of several targeted drugs, such as tyrosine kinase inhibitor or anti-PD-1 and anti-CTLA4 antibodies." (PMID 31802362, 2020). "They include action on primary tumor cells and modification of their metastatic capabilities and regulation of tumor cell homing to the bone via CXCR4." (PMID 33333962, 2020). "Namely, CD11b+/CXCR4+ myeloid cell accumulation in the primary tumor was correlated with reduced cytotoxic T-cell activity and poor overall survival in patients." (PMID 33233625, 2020). "At this point, plerixafor showed strong inhibition of tumor cell metastasis due to disrupt the CXCR4/CXCL12 axis." (PMID 32486408, 2020). "The median CXCR4 expression per tumor was 50% (IQR, 18–83%) in the cytoplasm and 11% (IQR, 0–42%) in the nucleus." (PMID 32188473, 2020). "In a lymphoma model, the CXCR4-transduced T cells showed enhanced tumour protection compared to control T cells." (PMID 32708397, 2020). "In other types of cancer, the CXCL12/CXCR4 signaling plays an important role in shaping the tumor microenvironment by macrophages." (PMID 33096815, 2020). "Mechanistically, CXCL12 acts on endothelial cells through its receptor chemokine (C-X-C motif) receptor 4 (CXCR4) and promotes trans-endothelial migration of tumor cells." (PMID 33123472, 2020). "CXCR4 is a seven-transmembrane G-protein coupled receptor, which is overexpressed by stromal cells and tumor cells in more than 20 different human cancers types." (PMID 31802362, 2020). "In the same study, it was shown that rh-CXCL12 and also CXCR4 agonists, pushed MTC cells to enter the G2/M cell cycle phase in a CXCR4-mediated manner and induced the expression of genes associated with EMT and tumor cell invasion." (PMID 32244473, 2020). "Up-regulation of CXCR4 has been related with activation of NF-κB, which can regulate tumor growth and survival." (PMID 32630806, 2020). "The diagnostic specificity for CXCR4 levels (69%) was higher than that for CXCR2 (66%) and the classical tumor marker (CEA–47%), but lower in comparison to CRP levels (94%), similarly to the predictive value for positive (PV+ve) results." (PMID 32867211, 2020). "Cancer cell CXCR4 overexpression contributes to tumor growth, invasion, angiogenesis, metastasis, relapse and therapeutic resistance." (PMID 32443455, 2020). "CXCR4 is involved in various biological processes, including immune cell trafficking, tumor growth, and metastasis." (PMID 31802362, 2020). "CXCR4 expression levels were significantly increased in tumor stromal cells and in tumor colonocytes, compared to matched cell types from adjacent normal-appearing mucosa." (PMID 32110952, 2020). "In this study, three anti-CXCR4 scFvs were obtained from the human scFv library by yeast two-hybrid system, and they showed anti-tumor effect in vitro and in vivo." (PMID 33392074, 2020). "Immunostaining showed both cytoplasmic and partially membranous staining of CXCR4 in the U937 tumor xenograft." (PMID 32321944, 2020). "Pharmacokinetic evaluation and dosimetry analyses of 211At-CXCR4 mAb revealed that the TIs, tumor-to-bone marrow and tumor-to-kidney, for the tumor of 10 g, were 44.5 and 79.4, and the TIs for the tumor of 20 g were 22.3 and 39.7, respectively." (PMID 32321944, 2020).
tumor (continued). "Tumor cells increase the CXCR4 levels and CXCL12 production, transmitting autocrine and paracrine signals, leading to enhanced tumor growth and metastasis." (PMID 33195200, 2020). "Recently, it was revealed that C-X-C motif chemokine receptor 4 (CXCR4) is one of the primary chemokine receptors involved in the enrollment and tumor tropism of MSCs." (PMID 33117154, 2020). "The estimated absorbed doses of 211At-CXCR4 mAb were 22.8 mGy/MBq in the tumor of 10 g and 11.4 mGy/MBq in the tumor of 20 g." (PMID 32321944, 2020). "Taken together, these observations demonstrate that huCAR19 NK cells augmented with CXCR4 are able to eradicate CD19+ tumor cells in a CAR-dependent manner, have significantly enhanced migration ability, and retain their functional activity post-migration." (PMID 32983147, 2020). "Contradictory results have been presented by other authors who revealed that CXCR4 expression significantly correlated with advanced stages of the disease and tumor progression." (PMID 32867211, 2020). "High levels of CXCR4, a receptor correlated with tumor malignancy, and CCL22, a member of the chemokine family, are related to migration, invasion, and metastasis in various tumors, leading to a poor prognosis and malignant progression." (PMID 32102251, 2020). "Activation of ACKR3 induces VEGF expression and tumor growth but impairs invasion contrary to CXCR4." (PMID 33096815, 2020). "In these models, CXCR4 inhibition resulted in rapid T cell infiltration and synergized with PD-L1 immunotherapy leading to better clearance of the tumor cells." (PMID 32483120, 2020). "Although the functions of CXCR4 are well described in tumor growth and invasion, the regulation of CXCR4 gene expression in cancer is less well understood." (PMID 32110952, 2020). "Our data showed that the MDA-MB-231 cells expressed higher levels of CXCR4 than did the non-tumor cell lines." (PMID 33195200, 2020). "Inhibition of CXCR4 induces promising anti-tumor response mainly by preventing recruitment of BMDCs in the tumor mass and must be considered as a future therapeutic option." (PMID 32775327, 2020). "In this present study, we showed that CXCR4 is overexpressed in GC tumor tissue, with a significant correlation between the CXCR4 levels and the survival rate, consistent with previous studies." (PMID 32306562, 2020). "VEGFC can, thus, be added to a growing list of tumor and metastatic proteins, including CXCR4 and MMP1, all of which are transcriptionally regulated by BACH1." (PMID 32132179, 2020). "CXCR4 overexpression promotes migration, adhesion, and invasion in tumor cells, besides promoting epithelium–mesenchyme transition and acting in tumor development." (PMID 33195200, 2020). "The main focus of current study was to develop radiolabeled the derivatives of Plerixafor and AMD3465 that crosses the BBB and tumor cell membranes for PET imaging of CXCR4." (PMID 32239371, 2020). "Among a number of chemokines and their receptors, CXCL12/CXCR4 signaling is an integral oncogenic communication network between a tumor and its stroma." (PMID 32260318, 2020). "The expression of CXCR4/CXCL12 in tumors is partially dependent on the hypoxic tumor microenvironment, in a HIF-1α dependent manner." (PMID 32983169, 2020). "Genetic engineering has been used to overexpress the chemokine receptor CXCR4 in tumour-specific CD8+ T cells, which promoted homing to bone marrow niches and preferential differentiation into memory T cells." (PMID 32708397, 2020). "Normalized CXCR4 transcript reads (FPKM values) served as the basis for comparing mRNA expression differences among the CRC that were categorized into 4 tumor stages." (PMID 32110952, 2020). "This increases in CXCR4 density is due to either increased expression of the receptors on tumor cells or increased tumor infiltration of CXCR4 expressing immune cells." (PMID 31802362, 2020).
tumor (continued). "This suggests that LASP1 inhibits Let-7a’s tumor suppressor function in response to CXCR4 activity in order to allow for induction of proteins that are involved in the process of cell motility and invasion." (PMID 32872485, 2020). "Nobiletin treatment on MDA-MB 231 cells reduces the expression of CXC chemokine receptor type 4 (CXCR4), which is highly expressed in cancer stem cell populations in tumor patients." (PMID 32212785, 2020). "ROS activation of the CXCL-12/CXCR-4 signaling pathway contributes to a cross-talk between tumor cells and CAFs." (PMID 33585565, 2020). "Previously, we have shown that particles functionalized with AMD3100 have enhanced retention in CXCR4-expressing tumor cells both in vitro and in vivo." (PMID 33134314, 2020). "Here, we have shown that local tumor irradiation indeed caused a significant increase in the accumulation of the CXCR4 selective probe N-[11C]methyl-AMD3465 in the tumor, indicating that the CXCR4 density in the tumor is increased." (PMID 31802362, 2020). "Whereas, CXCR4 was characterized as a typical tumor-supporting receptor, many lines of evidence indicated CXCR7/ACKR3 can have pro-metastatic effects but in specific settings it can act in an opposite manner." (PMID 32582148, 2020). "The immune checkpoint regulator programmed death-ligand 1 (PD-L1) is regarded as a novel promising therapeutic target and has been detected on CTC, and CXCR4 is an important receptor for tumor cell dissemination to the bone marrow." (PMID 32466213, 2020). "The CXCR4 is inevitably responsible for tumor cell invasion to the site of metastasis and tumor cell mobility (pseudopodia formation and actin rearrangement)." (PMID 32670883, 2020). "One of the inherent characteristics of MSCs is the ability to implant in tumor tissue that is dependent on multiple cytokine receptors such CXCR4 and matrix metalloproteinase-2 (MMP-2)." (PMID 32370750, 2020). "At the same time, CXCL12 can attract CXCR4-positive inflammatory, vascular, and stromal cells into the tumor mass to support tumor development." (PMID 33363463, 2020). "X4P-001(AMD3100) is an orally bioavailable CXCR4 antagonist that has demonstrated activity in various tumor models." (PMID 32575838, 2020). "Taken together, SETDB2 interacts with ΔNp63α, methylates and stabilizes the ΔNp63α protein to upregulate the Hedgehog pathway-associated genes CXCR4, PTCH1 and GLI2, which promote stem cell maintenance, tumor initiation and growth." (PMID 32549764, 2020). "For example, CFA secretion of transforming growth factor-β (TGF-β) potentiates CXCR4 stimulation of AKT signaling in human prostate epithelial cells, which indicates that synergism between TGF-β, CXCL12, and CXCR4 in tumor stroma contributes to carcinogenesis." (PMID 33363463, 2020). "In conclusion, CXCR4 and GPR183 were down-regulated in PCa tumors, and both of these genes were associated with tumor purity and immune cell infiltration." (PMID 33194726, 2020). "CXCR4 and its inhibition have been demonstrated in different tumor types to efficiently revert Treg suppression of T effectors proliferation, improving anticancer immune responses." (PMID 33123122, 2020). "After intravenous administration, AP30NPs selectively accumulated in BCBM through the interaction between AMD3100 and CXCR4 and transfected tumor cells." (PMID 32154067, 2020). "CXCL12/CXCR4 axis has been described to play a pivotal role in CSCs maintenance, to guide tumor cell dissemination, and to foster chemoresistance." (PMID 33123122, 2020). "Some clinical investigations have proved that CXCR4 overexpression in cancer cells contributes to tumor growth, invasion, angiogenesis and metastasis." (PMID 32867211, 2020). "The CXCR4/CXCL12 axis can promote tumor metastasis by mediating cell invasion and proliferation and also enhancing tumor-associated neoangiogenesis." (PMID 33195200, 2020).